ANKRD20A7P (ankyrin repeat domain 20 family member A7, pseudogene)
Gene: Transcribed unprocessed pseudogene on chromosome 9 (42,852,675 to 42,920,095, forward strand). Ensembl gene ENSG00000236816.
Diseases named in the same sentence as ANKRD20A7P in open-access papers:
ANKRD20A7P is named in the same sentence as 1 disease in open-access papers, as found by Europe PMC text mining. Sharing a sentence is not in itself a finding about the gene and the disease. The quoted sentences say what the papers report.
tumor (1 paper, 2025). "Based on the current knowledge, we assume the expression of ANKRD20A7P might be a regulatory factor either as antisense RNA or competing endogenous RNA that affects other tumor-related gene’s expression." (PMID 40622919, 2025).